IL6 (interleukin 6)
Diseases named in the same sentence as IL6 in open-access papers (continued):
Sharing a sentence is not in itself a finding about the gene and the disease.
systemic juvenile idiopathic arthritis (45 papers, 2009 to 2025). "Beyond, we cannot identify a significant association of seropositivity for anti-IL-1Ra antibodies with Still’s disease hallmark cytokine levels such as IL-6 or IL-18." (PMID 38231276, 2024). "The role of IL-6 is important in the inflammatory manifestations of CD, which can mimic Still disease, another IL-6–related condition with underlying autoinflammatory mechanisms." (PMID 32303241, 2020). "For Still's disease, the review highlights the transformative role of biologic therapies targeting IL-1 and IL-6 in reducing systemic inflammation and improving outcomes." (PMID 40370972, 2025). "Advances in biologic DMARDs (bDMARDs) have transformed Still's disease management, with IL-1 inhibitors (e.g., anakinra, canakinumab) and IL-6 inhibitors (e.g., tocilizumab) achieving rapid systemic control, and reducing corticosteroid dependence." (PMID 40370972, 2025). "In systemic juvenile idiopathic arthritis (sJIA) patients, elevated levels of IL-6 have been found in blood and synovial fluid, and they are associated with disease activity." (PMID 38605717, 2024). "Further, erythropoiesis-related genes are upregulated in PBMCs of patients with systemic-onset juvenile idiopathic arthritis (SoJIA), while active SoJIA-driven CECs co-cultured with healthy donor monocytes suppress IL-1β, IL-6, and IL-8 secretion." (PMID 39474425, 2024). "In patients with systemic juvenile idiopathic arthritis, high levels of IL-6 inhibit the cytotoxicity of NK cells and down-regulate the expression of granzyme B and perforin." (PMID 39346912, 2024). "Systemic juvenile idiopathic arthritis (SJIA) is a chronic inflammatory disease of childhood with elevated serum IL-6 levels." (PMID 37270663, 2023). "Inhibition of IL-1 or IL-6 has clearly demonstrated to be effective in controlling clinical and laboratory inflammatory manifestations of Still’s disease, with a strong glucocorticoid sparing effect and a tolerable safety profile." (PMID 36619631, 2022). "The treatment of systemic-onset JIA specifically has developed to include targeted therapies for interleukin-1 and interleukin-6, as these cytokines are recognized as playing an important role in the development of inflammation." (PMID 34946409, 2021). "In the cytokine storm or MAS states, including those linked to chimeric antigen receptor T-cell therapy (CAR-T) or Still’s disease, impressive responses have been reported with anti-cytokine therapy against interleukin 6 (IL-6) or interleukin 1 (IL-1)." (PMID 34501738, 2021). "They report that tocilizumab successfully blocks IL-6 signaling and has beneficial effects against rheumatoid and juvenile systemic idiopathic arthritis, and other chronic inflammatory conditions." (PMID 34253862, 2021). "Systemic-onset juvenile idiopathic arthritis (sJIA) is an autoinflammatory disease characterized by increased levels of interleukin(IL)-1 and IL-6." (PMID 28288653, 2017). "In the last decade, the discovery that IL-1 & IL-6 are key therapeutic targets in systemic juvenile idiopathic arthritis (SJIA) and the introduction of IL-1 and IL-6 inhibiting biologics have led to a dramatic improvement in the outcome of typical features of this disease." (PMID 38183096, 2024). "On a serum/plasma biomarker level Still’s disease is further hallmarked by elevated levels of bioactive, free IL-18 (not complexed by IL-18 binding protein (IL-18BP)); as well as S100 proteins, sCD163, IL-6, IL-8, IL-17, and TNF-α." (PMID 38231276, 2024). "Additionally, given the reported association between cytokine-like IL-1 and IL-6 inhibitors and HLA-DRB1*15 alleles in DRESS cases with Still’s disease, we should also explore the role of cytokines in these adverse reactions." (PMID 39188942, 2024).
systemic juvenile idiopathic arthritis (continued). "However, even in disease states for which IL-6 blockade is the standard of care (polyarticular juvenile idiopathic acrthritis (JIA), systemic onset JIA), IL-6 levels in sera samples obtained from patients with active disease are not always elevated." (PMID 39337619, 2024). "While the IL-6 antagonist tocilizumab has been proven to be effective in treating severe and persistent Still’s disease, tumor necrosis factor inhibitors have been proven to have some role but seem to be replaced by anti-IL-1 and anti-IL-6 agents in terms of systemic efficacy." (PMID 38148914, 2023). "Agents blocking IL-6 are also recommended and may represent a valuable option in patients refractory to other treatment choices, as for joint involvement in Still’s disease." (PMID 36619631, 2022). "Moreover, the high IL-6 level in the serum of the patients as well as the deterioration in NK-cell function in systemic juvenile idiopathic arthritis, which is a chronic inflammatory and autoimmune disorder, supports our view." (PMID 34174798, 2022). "Despite the lack of internationally shared treatment guidelines, the current approach supports the use of IL-1 inhibitors in patients with Still’s disease, while IL-6 antagonists may represent an effective treatment choice in refractory cases with persistent inflammatory joint involvement." (PMID 36619631, 2022). "The same study group carried out a multicenter case–control study including 66 patients with Still’s disease and features of IL1/IL6-inhibitor-related DRESS and 65 patients with drug-tolerant Still’s disease." (PMID 36553101, 2022). "Still’s disease, whose pathophysiology is dominated by macrophagic activation and the role of IL1 and IL6, is an excellent model for ferritin secretion." (PMID 35456325, 2022). "Interestingly, in patients with juvenile systemic idiopathic arthritis (SJIA), pulmonary involvement triggers a hyperinflammatory reaction and the appearance of secondary hemophagocytic lymphohistiocytosis (sHLH), as IFN, IL-1β, and IL-6 signature up-regulation can be observed." (PMID 34202243, 2021).
eosinophilia (44 papers, 2008 to 2026). "Taken together, our results demonstrate a beneficial effect of combined anti-TNF/IL-6 administration including reduced Th2-associated eosinophilia and Th17/Th1-mediated neutrophilic infiltrate in the airways." (PMID 35408882, 2022). "The high levels of IL6 mRNA were closely associated with gut eosinophilia and mastocytosis in the resistant strain of mice." (PMID 30012189, 2018). "At day 7 and 14, IL-6-deficient mice exhibited higher levels of MLNC eosinophilia than BALB/c mice, consistent with reports that IL-6−/− mice display enhanced lung eosinophilia during Schistosoma mansoni infection." (PMID 24185641, 2014). "In the asthmatic EMTU, the epithelial release of inflammatory cytokines (CCL-5, IL-1α, TNF-α, IL-8, and IL-6) can regulate mesenchymal inflammation to cause eosinophilia and TH2 inflammation (TSLP, GM-CSF) as well as neutrophilic inflammation (TNF-α, IL-8, IL-6)." (PMID 32679790, 2020). "Previous studies using an adoptive transfer of IL-6 deficient dendritic cells to WT mice, indicated the role of dendritic-cell-derived IL-6 in allergic inflammation, characterized by increased Th2 response and increased eosinophilia." (PMID 30534125, 2018). "To next evaluate the impact of IL-6 deficiency on the innate immune response to H. polygyrus infection, we then assessed the generation of eosinophilia, which in other helminth infections can occur independently of the adaptive Th2 compartment in nu/nu, STAT-6−/−, and RAG-deficient animals." (PMID 24185641, 2014). "Additionally, IL-6 was linked to the suppression of airway eosinophilia and specific IgE responses." (PMID 37046042, 2023). "Furthermore, pharmacological inhibition of IL-6 during airway inflammation was associated with a marked local increase in protein levels of IL-13, IL-4, and IL-5, which are critically involved in Th2-mediated eosinophilia." (PMID 35408882, 2022). "The cytokines such as IL-4, IL-5, and IL-13 are released causing eosinophilia and the pro-inflammatory cytokines like IFN-γ, TNF, IL-6, and IL-15 are increased promoting systemic inflammation." (PMID 41229508, 2025). "Blood eosinophilia was positively correlated with the serum concentrations of periostin (r = 0.35, p < 0.05), IL-6 (r = 0.49, p < 0.05), IL-10 (r = 0.66, p < 0.05), IL-12p70 (r = 0.39, p < 0.05), and ADAM33 (r = 0.59, p < 0.05)." (PMID 36835202, 2023). "On the other hand, BALB/C mice develop a predominant Th2 response, producing IL-4, IL-5, IL-6, favoring IgE production and eosinophilia." (PMID 36263051, 2022). "The activation of T lymphocyte and eosinophilia with increased peripheral proinflammatory cytokines IL-1β, IL-6 and TNF-α are identified as the main features of FD." (PMID 36091013, 2022). "The IL-6 trans-signaling large subset was overrepresented by frequent exacerbations, blood eosinophilia, and submucosal T cell and macrophage infiltration." (PMID 35052792, 2022). "Isolated studies have also reported eosinophilia secondary to irradiation, which typically orchestrates a T cell response to cancer and indirectly stimulates Il6." (PMID 30722781, 2019). "Complete genetic inactivation of IL-6 ameliorated the disease with significant decrease in eosinophilia in the lungs." (PMID 30534125, 2018). "Serum IL-4, IL-5, and IL-6 levels increased in the present case when MM developed with eosinophilia, and these cytokines and eosinophils decreased after the treatment of MM." (PMID 30376895, 2018). "Mice deficient in IL-6 also exhibited increased eosinophilia in the MLN, consistent with reports that IL-6-deficient mice display enhanced lung eosinophilia and parasite mortality following S. mansoni infection." (PMID 24185641, 2014). "In this study, we found that this subgroup exhibited not only an increase in the levels of inflammatory cytokines, such as IL-6 but also a profile indicative of type 2 inflammation, including peripheral blood eosinophilia and elevated serum IL-4 and IL-13 levels." (PMID 40278124, 2025).
eosinophilia (continued). "Unbiased single-cell sequencing analysis of controls and SP-CI73T mutants at a time coordinated with peak eosinophilia (14 days) defined heightened inflammatory activation, chemotaxis, and survival signaling (IL-6, IL-4/13, STAT3, Glucocorticoid Receptor, mTOR, and MYC) in eosinophils." (PMID 35571100, 2022). "This response could be promoted by IL-6 and may be accompanied by eosinophilia." (PMID 33718270, 2021). "Unexpectedly, we found that genetic ablation of macrophage-derived IL-6 ameliorated the disease with significant decrease in the number of total BAL fluid lymphocytes and in the eosinophilia of the respiratory tract." (PMID 30534125, 2018). "Immunological assays showed eosinophilia and an increase of CD4 cells but not an increase of the tumor causing cytokine IL-6 negating doubts of safety." (PMID 28324460, 2014). "Although more and more of the previously identified risk factors can be linked with the other phenotypes, ARAD (neutrophilia, IL-1β, IL-8, IL-6, and TNF-α, CRP) and RAS (eosinophilia, CRP), protein profiles observed in this and previous reports 27 do not show significant changes." (PMID 24750386, 2014). "In addition, infection indexes include leukocyte (WBC), neutrophil (Neut), lymphocyte (Lymph), eosinophilia (EO), C-reactive protein (CRP), procalcitonin (PCT), interleukin-6 (IL-6), and erythrocyte sedimentation rate (ESR) of all the negative samples were collected." (PMID 35651750, 2022). "Combined IL-6/TNF inhibition, but not individual blockade of these two cytokines, led to complex anti-inflammatory effects including reduced Th2-induced eosinophilia and less prominent Th17/Th1-mediated neutrophilic infiltrate in the airways." (PMID 35408882, 2022). "Treatment with IP results in eosinophilia and an increase of CD4 cells but not in an increase of IL-6 or CRP." (PMID 22114899, 2011).
nasopharyngeal carcinoma (44 papers, 2006 to 2026). A carcinoma arising from the nasopharyngeal epithelium. "Our previous study found that IL-6 was significantly increased in nasopharyngeal carcinoma patients after radiotherapy and was associated with post-irradiation vestibular dysfunction." (PMID 32977807, 2020). "RTA, an EBV immediate early transactivator that controls viral reactivation, has been found to drive transcription of the IL6 gene in cell lines derived from nasopharyngeal cancer." (PMID 36675141, 2023). "IL6 also upregulates the expression of MMPs and promotes the migration and invasion of nasopharyngeal carcinoma cell lines." (PMID 35008304, 2021). "In previous studies, miR-26a/b have been shown to block the G1/S transition of the cell cycle by targeting CCND2, CCNE1/2, CDK6, and EZH2 in HCC and nasopharyngeal carcinoma, and to restrain metastasis by suppressing the expression of IL6 in HCC." (PMID 24565101, 2014). "We demonstrated IL-6 modulated iNOS expression via STAT3 and EGFR in EBV-associated nasopharyngeal carcinoma." (PMID 25547488, 2014). "The nasopharyngeal carcinoma‐on‐a‐chip was unique in its design, employing electrodes for real‐time measurements of impedance, which facilitated real‐time monitoring of cell invasion and quantitative analysis of IL‐6's impact on intravasation." (PMID 39101627, 2024). "It is also known that IL-6 participates in the regulation of migration and invasiveness of several types of cancer cells, including nasopharyngeal carcinoma cells, in which blocking of the IL-6 receptor by a specific monoclonal antibody reversed both processes and also EMT." (PMID 31337349, 2019). "In nasopharyngeal carcinoma, loss of CRIP2 promotes tumorigenesis and angiogenesis by interacting with NF-κB/p65 and compromises NF-κB-mediated proangiogenic cytokine expression including IL6, IL8, and VEGF44." (PMID 29662084, 2018). "Moreover, MDSCs expanding are positively correlated with the elevated serum IL-6 levels in nasopharyngeal carcinoma." (PMID 29383101, 2017). "Nasopharyngeal carcinoma (NPC) is a neoplasm related to inflammation; the expression of cytokines, such as CCL3, CCL4, CCL20, IL-1α, IL-1β, IL-6, IL-8, and IL-10, among others, is presumed to be associated with NPC occurrence and development." (PMID 39483474, 2024). "Berberine exerted inhibitory effects on constitutive and IL-6-triggered activation of STAT3 in NPC (nasopharyngeal carcinoma) cells." (PMID 30987378, 2019). "The correlation between the IL-6 pathway, EMT, and radioresistance has previously been established in HNSCC, oesophageal and nasopharyngeal cancers." (PMID 39858048, 2025). "Cytokines such as IL-6, IL-8, IP-10, TNF-α, VEGF, EGFR, and MIP-3α were found to be elevated in nasopharyngeal carcinoma." (PMID 35964134, 2022). "Their study demonstrated that DANCR, acting as an oncogene in nasopharyngeal carcinoma, promoted nasopharyngeal carcinoma progression by interacting with STAT3 and enhancing JAK1 binding to STAT3 to strengthen IL-6/JAK1/STAT3 signaling." (PMID 33123287, 2020). "This promotes the induction of GM-CSF, IL-6, and IL-1β production through COX-2 and NLRP3 inflammasome signaling pathways to enhance MDSCs differentiation and expansion, thereby promoting nasopharyngeal carcinoma (NPC) progression." (PMID 31275326, 2019). "A previous study in nasopharyngeal carcinoma demonstrated that CRIP2 overexpression in cell lines transcriptionally and functionally down-regulated NF-κB–mediated proangiogenic proteins such as IL-6, IL-8 and VEGF." (PMID 26934316, 2016). "Nuclear accumulation of epidermal growth factor receptor (EGFR) and activation of STAT3 by IL-6 play a key role in iNOS expression and resultant DNA damage, leading to EBV-related nasopharyngeal carcinoma." (PMID 25547488, 2014).
nasopharyngeal carcinoma (continued). "Dephosphorylation of EGFR receptor at Y-1068 and Y-1086 in nasopharyngeal carcinoma inactivates the PI3K/Akt signaling cascade, resulting in the downregulation of proangiogenic pathways, invasive proteins including VEGF, IL-6 and IL-8, and suppressing tumour cell proliferation." (PMID 34389752, 2021). "This study is intended to explore the correlation of IL-6 and JAK2/STAT3 signaling pathway with clinicopathological features and prognosis in nasopharyngeal carcinoma (NPC)." (PMID 34165442, 2021).